BAP1 (BRCA1 associated deubiquitinase 1)
Diseases named in the same sentence as BAP1 in open-access papers (continued):
Sharing a sentence is not in itself a finding about the gene and the disease.
tumor (continued). "However, despite the number of studies indicating an important role of BAP1 in tumor suppression, recent studies also provided evidence for a potential gain of function of BAP1/ASXLs in myeloid malignancies." (PMID 33230107, 2020). "BAP1 (ubiquitin carboxyl-terminal hydrolase) is a deubiquitinase that acts as a tumor suppressor." (PMID 32139796, 2020). "In particular, BAP1 is thought to bind to the breast cancer type 1 susceptibility protein (BRCA1) and the BRCA1-associated RING domain protein 1 (BARD1) and enhance their tumor suppressor function." (PMID 32226777, 2020). "Well-defined tumor margins, nodular tumor enhancement, and intratumoral vascularization were associated with VHL mutations, while renal vein invasion was significantly associated with KDM5C and BAP1 mutations." (PMID 31901171, 2020). "Likewise, tumor-specific mutations have been found in the genes GNAQ, GNA11, EIF1AX, SF3B1, and BAP1." (PMID 33053887, 2020). "Furthermore, asbestos exposure of Bap1+/− animals resulted in accelerated, larger, and more aggressive tumor development with very high incidence and low survival rates." (PMID 32882916, 2020). "Disruption of the intricate balance of ubiquitin marks due to the loss-of-function of a DUB has been shown to severely impact DSB repair, and may promote cancer formation, as indicated by tumor suppressor functions of BAP1, USP16, and other DUBs." (PMID 32466590, 2020). "Importantly, SETD2 and BAP1 mutations displayed lower allelic burdens than coexisting VHL mutations, suggesting that these mutations are acquired at later times during tumor development." (PMID 32751108, 2020). "In order to identify correlations between selected miRNAs and the occurrence of these molecular events, we utilized tissue microarrays to perform FISH analyses to determine chromosome 3 status, and immunohistochemical staining for BAP1 expression among the UM primary tumor samples." (PMID 32131485, 2020). "Thus, lower levels of mRNA in UM indicated significantly worse overall survival, which was consistent with the role of BAP1 as a tumor suppressor in UM." (PMID 32028647, 2020). "The loss of BAP1 expression was associated with decreased ALT (alanine aminotransferase), AST (aspartate aminotransferase), TBIL and higher histological differentiation in large type of ICCs, while it was correlated to larger size of tumor in small duct type." (PMID 32293336, 2020). "Considering this, we checked the BAP1 gene expression from the TCGA dataset and found that regardless of the mutation type, an alteration of the BAP1 gene expression can be used for the prognosis in 29 tumor types." (PMID 31635116, 2019). "In the task of nuclear BAP1 expression recognition, clinicians have the challenge of counting the proportion of tumor cells with nuclear stain above the background, which may generate considerable intra- and interobserver variability." (PMID 31623293, 2019). "Soluble HLA is especially present in the aqueous humour of large tumours, which display ciliary body involvement, loss of chromosome 3, and negative BAP1 staining, and which have a higher chance of developing metastases." (PMID 31426578, 2019). "Understanding the function of PR-DUB is all the more important in view of the tumor-suppressive functions of BAP1 in several cancer types including uveal melanoma, mesothelioma, and clear-cell renal cell carcinoma and of ASXL proteins in hematologic malignancies." (PMID 30664650, 2019). "It would be interesting to investigate whether increased vascularity explains why some large, yet disomy 3/BAP1-positive tumours become metastatic." (PMID 31337000, 2019). "Adjusting for tumor purity (STAR Methods), we detected a trend of higher sample-wise correlation in tumors associated with clinical features such as higher grade (p = 0.006), chromosome 14 loss (p = 0.0006), and BAP1 mutations (p = 0.00004)." (PMID 31675502, 2019).
tumor (continued). "Pathogenic germline variants have been found to segregate with the disease in high risk RCC families in France and the US, indicating that RCC might be an integral part of the BAP1 tumor spectrum." (PMID 31034483, 2019). "Also, a recent meta-analysis of 26 BAP1 expression studies in 10 different cancer types concludes that the prognostic implication of BAP1 alterations depends on the tumor type." (PMID 31903168, 2019). "The high-risk group consisted of seven patients with a mean DFS of 28 months, a BAP1 mutated tumor, and a negative BAP1 immunohistochemistry (IHC)." (PMID 31212861, 2019). "Besides VHL, frequent genetic mutations have been detected in BAP1, PBRM1, and SETD2, all of which are related to chromatin and histone regulation and serve as tumor suppressor genes in kidney cancer." (PMID 31739630, 2019). "Olaparib induces superior apoptotic response in BAP1-mutant tumours in vitro." (PMID 30700254, 2019). "Similarly, BAP1-negative tumours (n = 23) had a higher MVD compared to BAP1-positive tumours (n = 20, p = 0.004)." (PMID 31337000, 2019). "BAP1 is one of the most important tumor suppression factors expressed by gene BAP1." (PMID 31623293, 2019). "Expression of HIF1a is increased in tumours with monosomy 3 and BAP1 loss, but not with gain of chromosome 8q." (PMID 31323773, 2019). "BAP1 depletion, however, triggers cell death in many cell types, which could seem paradoxical considering its tumor suppressor function." (PMID 31641107, 2019). "It has been suggested that the DNA-repair function of BAP1 may be the molecular basis for its tumor suppressor role in UM." (PMID 31382494, 2019). "If ≥33% were positive, the tumor’s BAP1 expression was classified as high." (PMID 31623293, 2019). "The role of genes RBM15B and USP19 may be important in BAP1 function and give further insight into the mechanism of BAP1 tumor suppression and additional targets for therapy." (PMID 30716094, 2019). "A new study finds that loss of the deubiquitinase BAP1 in PeM correlates with an inflammatory tumor microenvironment, suggesting that BAP1 status might identify PeM, and possibly PlM, patients who would benefit from ICI therapy." (PMID 30914057, 2019). "Second, we evaluated the role of chromosome 8q within the BAP1 expressing tumours." (PMID 31337000, 2019). "Interestingly, most of the mutations showed a very high evolutionary action (EA) score, which is consistent with the fact that BAP1 acts as tumor suppressor and harbors metastatic potential in combination with other factors." (PMID 31635116, 2019). "Research to date has primarily focused on the tumor-suppressing role of BAP1." (PMID 30013160, 2018). "This identified an additional hypermutated UM case (patient UVM_1).This tumor was carrying a BAP1 mutation and monosomy 3 as well as 474 SNVs (305 non-synonymous SNVs) corresponding to a 36-fold increase of SNVs as compared to the overall TCGA UM series." (PMID 29760383, 2018). "Notably, low expression of BAP1 significantly correlated with larger tumor size, presence of lymphatic metastasis, and advanced TNM stage, which are all predictors of poor prognosis of ICC after curative surgery." (PMID 30305612, 2018). "Indeed, in vivo xenograft studies using BAP1 expressing cells showed reduced tumor growth compared to the control cells." (PMID 29686263, 2018). "Our data demonstrated that BAP1 is a potential tumor suppressor in ICC." (PMID 30305612, 2018). "In this study, multivariate regression analysis showed that in addition to these classic tumor variables, the presence of somatic, but not germline, BAP1 mutations was significantly associated with metastasis (HR=2.20, P=0.02; HR=0.87, P=0.81, respectively)." (PMID 30477459, 2018). "In addition, the Bcl-2 expression in BAP1 tumor cells isolated from mice were reduced compared to the control cells in line with the elevated number of cleaved caspase-3 cells observed in BAP1 expressing tumor cells." (PMID 29686263, 2018).
tumor (continued). "One of the reasons that this could be such an interesting preventative opportunity is that the region of 3p loss invariably encompasses all four tumor suppressor genes of VHL, PBRM1, BAP1, and SETD2, and hence spans at least 40 Mb." (PMID 29656891, 2018). "Xenograft studies confirmed that the expression of BAP1 reduces tumor growth and progression in vivo by lowering the levels of pro-survival factors such as Bcl-2, which in turn diminish the survival potential of the tumor cells." (PMID 29686263, 2018). "In conclusion, BAP1 is a putative tumor suppressor of ICC, and may serve as a valuable prognostic biomarker as well as potential therapeutic target for ICC." (PMID 30305612, 2018). "In studies where DNA from both tumor tissue and blood was sequenced to rule out the presence of germline mutations, the frequency of somatic BAP1 mutations was considerably higher than that observed in tumors with germline mutations, approaching 50%." (PMID 30477459, 2018). "Though germline BAP1 mutations have been described in patients with familial RCC and no other BAP1-related tumours, such cases are rare and BAP1 mutation analysis is not yet performed in all cases of inherited RCC." (PMID 29680948, 2018). "BAP1 has multiple properties, including tumour suppressor activity." (PMID 30060843, 2018). "Cox multivariate analysis showed in addition to chromosome-3 monosomy and larger tumor diameter, the presence of BAP1 somatic, but not germline mutations, was significantly associated with risk of metastasis(P=0.02)." (PMID 30477459, 2018). "The tumor suppressor activity of BAP1 requires deubiquitylation activity and nuclear localization." (PMID 28229253, 2017). "This basic knowledge has helped unravel BAP1’s role in tumor suppression in vivo." (PMID 29166932, 2017). "Overexpression of BAP1 can suppress tumor growth in mouse xenografts." (PMID 29159179, 2017). "It is interesting that PBRM1, BAP1, and SETD2 are all located at chromosome 3p, close to the 3p25 locus, indicating that these tumor suppressors might be functionally linked." (PMID 28846693, 2017). "It was hypothesized that BAP1 tumor suppressor activity could reside, at least in part, in stabilizing proteins through its poly-deubiquitinase activity." (PMID 29069806, 2017). "A polyclonal antibody of the neo-peptide of BAP1 were produced in rabbits and showed a good antibody-neoantigen specificity, which indicates that the neo-peptide of BAP1 could be a potential tumour-specific neoantigen." (PMID 28484631, 2017). "It will also be very informative to determine whether these newly described BAP1 functions take place in other tumor types or are context dependent." (PMID 29069806, 2017). "PBMR1 mutant tumours are associated with increased activity of TFs/(phospho)proteins that have roles in interleukin signalling and MYC, while regulators with increased activity in BAP1 mutant tumours are involved in DNA damage response, apoptosis, insulin signalling and mTOR signalling." (PMID 28139702, 2017). "BAP1 encodes a nuclear ubiquitin carboxyterminal hydrolase, which is a class of deubiquitinating enzymes, and contains binding domains for BRCA1 and BARD1 to form a tumor suppressor complex among other functions." (PMID 28302097, 2017). "However, later studies showed that although BAP1 was a tumor suppressor that played a role in BRCA1-mediated processes, it performed BRCA1-independent functions as well." (PMID 28404968, 2017). "Both the lack of consistent transcriptomic consequences and the identification of several poly-deubiquitinated targets led to the hypothesis that BAP1 tumor suppressor function could reside, at least in part, in its ability to stabilize target proteins." (PMID 29069806, 2017). "On the other hand, the downregulated expression of BAP1 was reported to have connection with carcinogenesis and EMT progression, suggesting that BAP1 may serve as a tumor suppressor gene implicated in the development of human cancers." (PMID 29159179, 2017).
tumor (continued). "Notably, NFE2L2 TF activity was significantly higher in BAP1 mutant tumours than PBMR1 mutant tumours." (PMID 28139702, 2017). "A recent study has shown that somatic mutations within BAP1 are related to tumor progression, but they do not define a category of patients with a worse outcome." (PMID 27993167, 2016). "Overexpression of BAP1 was shown to suppress tumor cell expansion in mouse xenografts." (PMID 26885612, 2016). "In cancer, BAP1 can function as both a tumor suppressor and a metastasis suppressor." (PMID 26885612, 2016). "SETD2 or BAP1 mutation alone did not discern tumour subsets with significantly different clinical outcomes in this uRCC cohort." (PMID 27713405, 2016). "We emphasize that using this approach a tumour is only considered BAP1 negative by IHC if all neoplastic cells show loss of expression of BAP1 and there is a positive internal control in non-neoplastic cells." (PMID 26982343, 2016). "In our series, two cases showed nuclear BAP1 staining in about 80 % of tumor cells and an underlying BAP1 mutation can thus not completely be ruled out." (PMID 26769193, 2016). "Immunohistochemistry (IHC) of MM tissues showed only cytoplasmic BAP1 staining and lack of nuclear BAP1 staining, suggesting that the remaining wild-type allele had also become altered in the tumor cells." (PMID 26683624, 2015). "That is, enrichment in BAP1 mutations is associated with late tumor stages but does not define per se a patient's outcome." (PMID 25826081, 2015). "Taken together, BAP1 may have a context-dependent function in terms of regulating tumour initiation and progression." (PMID 26419610, 2015). "Our results indicated that germline truncation and missense variants in several genes were under selection in the tumour, with ATM, BRCA1, BRCA2 and RAD51C determined as significant from both truncation and missense analyses and BAP1, BRIP1, FANCM, PALB2 and RAD51D from truncation analysis alone." (PMID 26689913, 2015). "Importantly, BAP1 stable knockdown suppressed tumour growth in HCC1806 cells and inhibited lung metastasis in 4T1 cells." (PMID 26419610, 2015). "It is clear that KLF5 knockdown inhibits tumour growth much more than BAP1 knockdown in this model." (PMID 26419610, 2015). "Immunohistochemical (IHC) analysis of BAP1 protein showed intact nuclear expression in tumor cells." (PMID 25798586, 2015). "Transcription of specific genes like MCM3 and CDKN1B effects tumor suppressor ability of BAP1." (PMID 26680512, 2015). "One cancer, P17, had acquired two small regions of deletion, one around SETD2 and the other around BAP1, although we did not detect pathogenic SNVs of either gene in this tumour." (PMID 25790038, 2015). "Also, a recent study showed that BAP1 and SETD2 mutations tend to appear late in tumor development, a finding that supports our observation." (PMID 25826081, 2015). "BAP1 mutations are related to tumor progression but do not define a category of patient with a worse outcome." (PMID 25826081, 2015). "Therefore, it appears that, to function as a tumor suppressor, BAP1 must maintain both nuclear localization and deubiquitylating activity." (PMID 26683624, 2015). "These two examined functions of BAP1 could explain tumor progression due to altered BAP1 expression." (PMID 25593912, 2014). "Thus, based on the binomial calculation, in order to detect a mutation in PBRM1, SETD2, BAP1, and/or KDM5C with 90% certainty, a tumor would need to be genetically profiled in at least three locations." (PMID 25124064, 2014). "However, the mechanistic contribution of BAP1 to tumor aggressiveness remains elusive." (PMID 41726922, 2026).
tumor (continued). "Indeed, our in ovo data confirmed this hypothesis in BAP1-deficient ccRCC cells treated with the Tat-BECN1 peptide, as tumor growth was significantly compromised compared to the Tat-scrambled peptide control." (PMID 40754831, 2025). "However, it is unlikely that comparable assays can be developed to generically detect all BAP1 mutations, as these mutations do no occur at hotspot positions and are practically unique in each mutant tumour." (PMID 40240901, 2025). "The inactivation of BAP1 leads to poor cell cycle regulation and cell proliferation, resulting in tumorigenesis, characterizing a clinically unique subtype of ccRCC, marked by aggressive characteristics and an inflammatory but immunosuppressed tumor microenvironment." (PMID 41440218, 2025). "Interestingly, both tumor components showed LOH of Chr 3p, suggesting that a potential splice variant of mutant BAP1, predominantly found in the thyroid SCC tumor, may be pathogenic in the PTC‐SCC transition." (PMID 40600748, 2025). "Furthermore, the therapeutic response was the most effective in case of BAP1-mutant tumors even after the relative tumor growth rate was adjusted, which may be attributed to the mechanism of action of OVs." (PMID 40856833, 2025). "However, the mutation status of the primary tumor, e.g., the presence of a BAP1 mutation, did not correlate with any of these growth patterns, while the loss of chromosomal 1p and 8p was much more pronounced in patients with military metastasis." (PMID 39056751, 2024). "In addition to large-scale proteome and transcriptome analysis, studies assaying BAP1 localization and deubiquitinating activity have uncovered several essential functions, diverse protein interactions, and downstream targets mediating BAP1 tumor suppression." (PMID 37956408, 2024). "Likewise, the tumor suppressive effects of BAP1 and NFS1 rely on the regulation of ferroptosis." (PMID 38267442, 2024). "Notably, BAP1 was also identified as a ferroptosis-related gene, which could suppress tumor progression through triggering ferroptosis." (PMID 38642144, 2024). "Additionally, silencing of BAP1 could reverse circ_0087851-induced tumor suppression and ferroptosis enhancement." (PMID 38642144, 2024). "Further analysis into public single cell transcriptomic dataset validated that UM tumor cells express 4-1BBL and its gene expression is associated with the unfavorable molecular characteristics such as GEP class 2, PRAME expression, loss of chromosome 3 and BAP1 mutation." (PMID 38191418, 2024). "In this case, the BAP1 mutant phenotype may result, and cells with this genotype are more advantageous under selection pressure from the immune-system and other factors, accelerating tumor progression." (PMID 38333293, 2024). "However, more recent published studies indicated that the tumor suppressor function of BAP1 is controversial and might be cell type- and context-dependent." (PMID 37543638, 2023). "Interestingly, in a small percentage of patients, BAP1 and PBRM1 mutations may coexist and in these cases, the resulting neoplasm manifests rhabdoid features." (PMID 37887570, 2023). "Recent studies suggest that BAP1 might also play tumor-promoting roles in certain types of cancer." (PMID 36754982, 2023). "However, the consequences of BAP1 and PBRM1 mutations on overall tumor cell chromatin accessibility and associated transcriptome changes in ccRCC are largely unknown." (PMID 36973268, 2023). "Moreover, BAP1 mediates the metabolic regulation of ferroptosis and tumor suppression." (PMID 35414786, 2022).